MAN2A2 (mannosidase alpha class 2A member 2)
Description:
Catalyzes the first committed step in the biosynthesis of complex N-glycans. It controls conversion of high mannose to complex N-glycans; the final hydrolytic step in the N-glycan maturation pathway.
Synonyms: MANA2X; HsT19662; alpha-MIIx
Tractability: Antibody: UniProt predicts a signal peptide or a membrane-spanning region. PROTAC: ubiquitination databases record sites on it; its protein half-life has been measured.
Gene: Protein-coding gene on chromosome 15 (90,902,218 to 90,922,585, forward strand). Ensembl gene ENSG00000196547.
Subcellular location: Golgi apparatus membrane
Subcellular location (Human Protein Atlas): Cytoplasmic bodies
Pathways (Reactome):
Metabolism of proteins: Reactions specific to the complex N-glycan synthesis pathway
Vesicle-mediated transport: Intra-Golgi traffic
Gene Ontology:
Molecular function: protein binding; alpha-mannosidase activity; carbohydrate binding; hydrolase activity, hydrolyzing N-glycosyl compounds; mannosidase activity; mannosyl-oligosaccharide 1,3-1,6-alpha-mannosidase activity
Biological process: N-glycan processing; carbohydrate metabolic process; mannose metabolic process
Cellular component: Golgi membrane
Genetic constraint (gnomAD): Loss-of-function variants: 79 observed, 131.94 expected, observed/expected ratio (o/e) 0.6, 90% interval 0.5 to 0.72. The upper end of that interval is the gene's LOEUF score, 0.72, which puts it in group 2 of 6, group 1 being the genes least tolerant of losing a copy. Missense variants: 1,392 observed, 1,590.9 expected, observed/expected ratio (o/e) 0.87, 90% interval 0.84 to 0.92. Synonymous variants: 671 observed, 650.38 expected, observed/expected ratio (o/e) 1.03, 90% interval 0.97 to 1.1.
Gene-disease validity (ClinGen):
ClinGen rates the evidence that MAN2A2 causes each of these diseases.
congenital disorder of glycosylation (autosomal recessive): Limited. Congenital disorder of glycosylation (CDG) is a fast growing group of inborn errors of metabolism characterized by defective activity of enzymes that participate in glycosylation (modification of proteins and other macromolecules by adding and processing of oligosaccharide side chains).
Homologues: Orthologues: chimpanzee MAN2A2 (99% identical), macaque MAN2A2 (98% identical), dog MAN2A2 (90% identical), rat Man2a2 (90% identical), mouse Man2a2 (90% identical), guinea pig MAN2A2 (88% identical), pig MAN2A2 (88% identical), rabbit MAN2A2 (83% identical), tropical clawed frog man2a2 (75% identical), zebrafish man2a2 (69% identical), Drosophila melanogaster alpha-Man-IIa (38% identical), Caenorhabditis elegans aman-2 (37% identical), and 1 more. Paralogues in human: MAN2A1 (54% identical), MAN2B1 (24% identical), MAN2B2 (23% identical), MAN2C1 (15% identical).
Diseases named in the same sentence as MAN2A2 in open-access papers:
MAN2A2 is named in the same sentence as 16 diseases in open-access papers, as found by Europe PMC text mining. Sharing a sentence is not in itself a finding about the gene and the disease. The quoted sentences say what the papers report.
myocardial infarction (3 papers, 2021 to 2024). Gross necrosis of the myocardium, as a result of interruption of the blood supply to the area, as in coronary thrombosis. "Recently, MAN2A2 has been identified as a factor associated with myocardial infarction and is upregulated during myocardial infarction; this finding is similar to our results." (PMID 38715006, 2024). "In this study, we identified 30 MOFA factors and 10 were associated with myocardial infarction; one of them included three genes that were also included in the factor 27 of the FOS cohort: CDC42BPB, MAN2A2, and RPTOR." (PMID 33836805, 2021). "Meeting all the cutoff criteria across all the data set analyzed, MAN2A2/TNFRSF12A/SPP1/CSNK1D/PLAUR/PFKFB3/CXCL16 (herein we termed it MTSCPPC signature) was identified as a novel pathological signature of myocardial infarction and was used for subsequent analyses." (PMID 35163208, 2022). "Moreover, in a replication effort in an independent study three of the genes included in factor 27 were also present in a factor identified to be associated with myocardial infarction (CDC42BPB, MAN2A2 and RPTOR)." (PMID 33836805, 2021).
autism spectrum disorder (1 paper, 2025). A spectrum of developmental disorders that includes autism, and Asperger syndrome. "Recent studies have linked MAN2A2 dysfunction to a range of neurological phenotypes, including autism spectrum disorders, cognitive delay, and congenital disorders of glycosylation (CDG)." (PMID 40870030, 2025).
diabetes (1 paper, 2025). "Additionally, 7 CpG sites annotated to MAN2A2, ABCG1, DENND3, NCOR2, BAIAP2 and CPT1A were linked to changes in diabetes status." (PMID 39827095, 2025). "Notably, among the seven CpG sites liked to the diabetes progression, five showed a negative correlation with gene expression levels, including cg23436042, cg11183227 (MAN2A2), cg06500161 (ABCG1), cg06710464 (BAIAP2), and cg17058475 (CPT1A), while cg08788930 (DENND3) and cg11311053 (NCOR2) did not." (PMID 39827095, 2025).
infertile (1 paper, 2024). "Inactivation of either the Mgat1 or Man2a2 gene leads to a block in spermatogenesis causing infertility in male mice." (PMID 39364139, 2024). "Man2a2-null males are produced in low numbers and are infertile." (PMID 39364139, 2024).
Insulin resistance (1 paper, 2019). Increased resistance towards insulin, that is, diminished effectiveness of insulin in reducing blood glucose levels. "Together, these findings suggest that regulating the differential methylation level or expression level of MAN2A2 may be relevant to the development of insulin resistance." (PMID 31197173, 2019).
liver disease (1 paper, 2021). "GLT8D2 and MAN2A2 have been implicated in non-alcoholic fatty liver disease and coinfected liver disease, respectively." (PMID 33705408, 2021).
cancer (1 paper, 2024). A tumor composed of atypical neoplastic, often pleomorphic cells that invade other tissues. "The expression levels of MAN2A2 were associated with increased drug sensitivity according to the Genomics of Drug Sensitivity in Cancer (GDSC) database." (PMID 38715006, 2024).
MAN2A2 also shares sentences with these, for which no sentence is quoted: cognitive delay (1 paper); hepatocellular carcinoma (1); liver fibrosis (1); neoplasia (1); non-alcoholic fatty liver disease (1); prediabetes (1); respiratory failure (1); schizophrenia (1); Walker-Warburg syndrome (1).